AKR1B10 (aldo-keto reductase family 1 member B10)
Diseases named in the same sentence as AKR1B10 in open-access papers (continued):
Sharing a sentence is not in itself a finding about the gene and the disease.
tumor (continued). "Therefore, we speculated that HOXA5 may also function as a tumor suppressor in ACC via targeting AKR1B10 and enhancing its expression level." (PMID 34027794, 2021). "Furthermore, studies have demonstrated that AKR1B10 was also related to tumor growth and metastasis, which may explain the lasting role in NAFL-NASH-HCC progression." (PMID 33574818, 2020). "Indeed, the paradoxical role of AKR1B10 in HCC tumor prognosis is well recognized." (PMID 30959792, 2019). "Via its ability to detoxify lipid peroxidation products by reduction of the carbonyl-groups to the corresponding alcohol metabolite, increased AKR1B10 activity could serve to protect tumour cells from oxidative stress-induced damage and cytotoxicity and permit maintained FAO activity." (PMID 31221959, 2019). "In summary, AKR1B10 is negatively correlated with differentiation, tumor growth and lymph node metastasis by inhibiting cell proliferation and migration of NPC, and therefore, AKR1B10 may be a valuable clinicopathological and prognostic indicator in patients with NPC." (PMID 26949513, 2016). "Moreover, expression of AKR1B10 is considered to be a tumor marker for NSCLC and liver tumors." (PMID 27562730, 2016). "Therefore, AKR1B10 is a potential tumor biomarker and therapeutic target." (PMID 26949513, 2016). "This suggests that AKR1B10 may play a dual role during HCC tumor progression." (PMID 26516929, 2015). "Immunofluorescence staining confirmed the downregulation of both AKR1B10 and LDHA protein levels in the combination group within the LR PDX tumours." (PMID 41454479, 2026). "In the Asian population, upregulated genes such as AKR1B10, UBE2C, and S100P are involved in immune modulation and tumor progression." (PMID 41216224, 2025). "We identified five tumor EPC subtypes using cell markers: C0 TSPAN1+, C1 AKR1B10+, C2 TOP2A+, C3 PTPRC+, and C4 LRMP+." (PMID 40777026, 2025). "We further investigated and analyzed the EPCs subtypes, categorizing them into C0 TSPAN1+ Tumor EPCs, C1 AKR1B10+ Tumor EPCs, C2 TOP2A+ Tumor EPCs, C3 PTPRC+ Tumor EPCs, and C4 LRMP+ Tumor EPCs." (PMID 40777026, 2025). "Validation analysis confirmed the up-regulation of model genes, including AKR1B10, ARL6IP4, ATP6V0B, and BSG in tumor tissues." (PMID 38913193, 2024). "In addition to the tumor itself affecting AKR1B10, external factors such as therapeutic means and therapeutic drugs, and the nutritional status of the patient may also have an effect on the differential expression of AKR1B10 between different tumors." (PMID 39737179, 2024). "This study aims to explore the expression characteristics of AKR1B10 in HCC and its correlation with clinicopathological features, survival prognosis, and tumor immune microenvironment, further investigating its role and potential regulatory mechanisms in HCC." (PMID 38802416, 2024). "In the TCGA dataset, the expression levels of AKR1B10, ARL6IP4, ATP6V0B, and BSG were significantly up-regulated in the tumor samples." (PMID 38913193, 2024). "A further comparison with blood NK cells revealed that only the potential HCC marker protein AKR1B10, which was also enriched in TAMs, and AFAP1L2, a cytosolic signaling scaffold protein, were specifically upregulated in tumor-infiltrating NK cells." (PMID 37388918, 2023). "Reduced mRNAs in most tumor samples included ADH4, ADHIB, ADHIC, and RDHL (for oxidation of all-trans retinol to all-trans retinaldehyde), and AKR1B10, AKR1B1, and RDH12 (for reduction of all-trans retinaldehyde to all-trans retinol)." (PMID 37569466, 2023). "Elevated METTL3 expression promotes tumor growth and glycolysis in CCA through m6A modification of AKR1B10, indicating that METTL3 is a potential target for blocking glycolysis for application in CCA therapy." (PMID 36476503, 2022).
tumor (continued). "Subsequently, we analyzed DEGs between tumor and normal tissues and selected the top five DEGs with the highest expression, which were SPP1, AKR1C2, AKR1B10, AGT, and EPHX1 in tumor tissues and NKG7, KLRD1, KLRB1, CCL5, and CST7 in normal tissues." (PMID 35967424, 2022). "While in tumor tissues, the higher grade of tumor is, the lower expression level of CBX7, but the higher expression level of AKR1B10 were detected." (PMID 34035231, 2021). "We also demonstrated for the first time that CBX7 acted as a tumor suppressor in UBC through the inhibition of cell proliferation, invasion, and stemness, via transcriptionally suppressing the expression of AKR1B10–ERK signaling." (PMID 34035231, 2021). "Collectively, it can be proposed that under-expression of both circ_0001666 and circ_0000977, as tumor suppressive circRNAs, contributes to the down-regulation of some tumor suppressive genes in CRC, including RASSF2, IL10RA, and AKR1B10." (PMID 33968341, 2021). "This study also showed that AKR1B10 inhibits glucose-deprivation autophagy by interacting with GAPDH, and suggested that low AKR1B10 expression in CRC promotes tumor development by upregulated autophagy." (PMID 34063865, 2021). "Our results shows that AKR1B10 overexpression in NPC cells resulted in increased Chk1 activation phosphorylation after 4 h of IR, stronger DNA repair ability, decreased tumor cell apoptosis, and enhanced radioresistance." (PMID 33767586, 2021). "Specifically, AKR1B10 targets ERK signalling to regulate lipid metabolism, a role that appears to be carcinogenic in many tumours." (PMID 32547320, 2020). "In this study, AKR1B10 expression levels in 135 pairs of CRC and para-tumor tissues were examined, and its oncogenic role was determined using in vitro and in vivo functional assays following genetic manipulation of CRC cells." (PMID 32615540, 2020). "In an analysis involving children and older adults (≥80 years), AKR1B10 protein levels differed between HCC tissues and near-tumor tissues for HCC patients." (PMID 30959792, 2019). "Conversely, AKR1B10 has been shown to be overexpressed in multiple cancers, particularly in NSCLC, promoting tumor growth and progression." (PMID 30692511, 2019). "Knockdown of AKR1B10 in Huh7 cells abrogated IRAK1-mediated sphere-forming ability, resistance to the tyrosine kinase inhibitor, sorafenib, and marker expression of tumor-initiating cells compared to normal Huh7 cells." (PMID 30959792, 2019). "Paraffin-embedded tissue blocks were available for 96 of the 110 patients, so AKR1B10 protein expression was semi-quantitated by immunohistochemistry in 96 pairs of HBV-related HCC and adjacent non-tumor tissues as well as in 8 cases of normal liver tissue." (PMID 28181486, 2017). "Levels of AKR1B10 mRNA were measured in 110 pairs of HBV-related HCC and adjacent non-tumor tissues as well as in 8 samples of normal liver tissue." (PMID 28181486, 2017). "Data showed that tumor size (≥5 cm), PVTT (yes) and AKR1B10 mRNA expression level (high) were independent predictors for DFS and OS." (PMID 26948042, 2016). "AKR1B10, AKR1C1, AKR1C2 and AKR1C3 constitute some of the most inducible targets of NRF2 in human systems, both normal and tumour-derived." (PMID 27824809, 2016). "In this study, we found that AKR1B10 plays an important role in 14-3-3ε-induced cell proliferation and HCC tumor growth." (PMID 26516929, 2015). "We discovered that AKR1B10 is regulated by 14-3-3ε/β-catenin signaling and that AKR1B10 contributes to 14-3-3ε-induced HCC cell proliferation and tumor growth." (PMID 26516929, 2015).
tumor (continued). "AKR1B10 knockdown significantly suppressed 14-3-3ε-induced HCC tumor growth, tumor volume and tumor weight." (PMID 26516929, 2015). "The four most upregulated genes were pepsinogen C (PGC), alpha fetoprotein (AFP), aldoketo reductase family 1 member B10 (AKR1B10) and glypican 3 (GPC3), which showed greater than 30-fold higher expression in HCC tumors than adjacent non-tumor tissues." (PMID 25217841, 2014). "Among the upregulated genes, PGC, AFP, AKR1B10 and GPC3 showed more than 30-fold increased expression in the HCC tumor group." (PMID 25217841, 2014). "Conversely, a trend toward improved OS was observed in patients showing tumor AKR1B1 (competitive inhibitor of AKR1B10) expression, although the difference was again not statistically significant." (PMID 40142797, 2025). "To identify transcription factors (TFs) mediating AKR1B10’s regulation of integrin expression, we analyzed proteins that bind integrin gene promoters in HCT116 cells and the ITGB8 promoter across various tumor cell lines using the chromatin immunoprecipitation (ChIP)–Atlas database." (PMID 40845116, 2025). "Small-molecule inhibitors, including AKR1B10 inhibitors (e.g., statil, epalrestatl) 43 and CYP1B1 inhibitors (e.g., flavonoids, trans-stilbenes) 44, have shown preclinical efficacy in suppressing tumor growth." (PMID 39744163, 2025). "Correspondingly, AKR1B10-positive GC specimens were more frequently from patients with a tumor size <5 cm, no lymph node metastasis, no distant metastasis, and a low tumor stage." (PMID 37039038, 2023). "Moreover, AKR1B10 was an m6A-related target of METTL3, and knockdown of AKR1B10 rescued the tumor-promoting effects induced by METTL3 overexpression." (PMID 36476503, 2022). "CTSF and AKR1B10 staining were notably dominant in the cytoplasm of tumour cells while FBLN1 staining was also observed in the interstitial cells in addition to the cytoplasm of tumour cells." (PMID 35217799, 2022). "Since both AKR1C3 and AKR1B10 were elevated in liver tumor tissues 50, an interplay between AKR1B10 and AKR1C3 by balancing FAO and glycolysis might be required to adapt to differential tumor environments and metabolic demands." (PMID 36451864, 2022). "We examined the expressions of CTSF, FBLN1 and AKR1B10 in BM tissues of 47 patients with NSCLC BM using IHC (cohort 3); 10 of these patients underwent orthotopic tumour excision in the early stages of the disease and the corresponding primary tumour tissues were also obtained." (PMID 35217799, 2022). "Thus, compared to matched normal tissue, the mRNA levels for AKR1B10 and AKR1C1 were decreased in 39/48 and 28/48 tumour samples, respectively." (PMID 35204145, 2022). "Better tumor regression was found to be higher in patients with negative AKR1B10 expression than in those with positive AKR1B10 expression (60% versus 40%, p = 0.033)." (PMID 36661656, 2022). "We realized that the serum level of AKR1B10 was correlated to its expression in tumor tissues, but not to the tumor size." (PMID 35280770, 2022). "Both mRNA and protein levels of AKR1B10 were significantly higher in tumor breast tissues than adjacent non-tumor counterparts." (PMID 34419144, 2021). "AKR1B10 and AKR1B1 are closely related to inflammation, and AKR1B10 in particular regulates inflammatory factors in the tumor microenvironment, which mobilizes the host immune response and promotes tumor suppression." (PMID 32615540, 2020). "Given this negative correlation between AKR1B10 expression and lipid synthesis, AKR1B10High tumour cells must rely either on increased uptake of exogenous fatty acids or increased release from intracellular fatty acid stores." (PMID 31221959, 2019).
tumor (continued). "IHC assay presented a signigicantly higher expression of AKR1B10 in HCC tumor tissues compared to the adjacent non-cancerous tissues." (PMID 30038373, 2018). "To validate the discoveries from the database mining, we explored the expression pattern of AKR1B10 by using IHC assay in our 53 paired HCC tumor and non-cancerous tissue samples." (PMID 30038373, 2018). "By stratified analyses, we further found that the expression of AKR1B10 significantly influenced early tumor recurrence in our patients with BCLC stage A HCC, but not in our patients with stage B or C disease." (PMID 28181486, 2017). "Mean AKR1B10 mRNA level by quantitative reverse transcription polymerase chain reaction (qRT-PCR) was 11.77 ± 3.79 in HCC tissues, significantly higher than the level of 8.45 ± 2.78 in adjacent non-tumor tissues (P < 0.001)." (PMID 28181486, 2017). "This hypothesis was also confirmed by the observation that AKR1B10 and S1P levels were much higher in PHC tissues than in peri-tumor tissues." (PMID 26948042, 2016). "To understand whether this observation is clinically significant, we investigated AKR1B10 gene expression in PHC tissues, and observed that mRNA level of AKR1B10 was higher in human PHC tissues than in peri-tumor tissues (99 in 144, 68.8%)." (PMID 26948042, 2016). "AKR1B10 and S1P expression levels were higher in PHC tissues than in peri-tumor tissues." (PMID 26948042, 2016). "We next studied whether 14-3-3ε-induced AKR1B10 expression is involved in regulating HCC cell proliferation and tumor growth." (PMID 26516929, 2015). "We found that the decrease in RA production may be involved in AKR1B10-induced HCC cell proliferation and tumor growth." (PMID 26516929, 2015). "Our results indicate that 14-3-3ε-induced AKR1B10 promotes HCC cell proliferation and tumor growth." (PMID 26516929, 2015). "The heightened expression of AKR1B10 in HCC is not only related to significant clinical-pathological traits but may also influence HCC progression and prognosis by activating key signaling pathways and altering the tumor immune microenvironment." (PMID 38802416, 2024). "In addition, a accurate validation about the impact of AKR1B10 on growth of GC cells and tumor metastasis is still lacking." (PMID 34552036, 2021). "Interestingly, this miRNA might post-transcriptionally inhibit two tumor suppressor genes, i.e. IL10RA and AKR1B10 in CRC." (PMID 33968341, 2021). "Furthermore, in a certain of non-gastrointestinal tissues, the expression of AKR1B10 in most tumor tissues was higher in comparison to normal tissues." (PMID 34552036, 2021). "Thus, we report AKR1B10 modulated regulated by miR-383-5p, promotes HCC tumor progress, and could be potentially a therapeutic target for precision medicine in HCC." (PMID 30038373, 2018). "According to the negative correlation of AKR1B10 expression levels and tumor node metastasis, we thought that AKR1B10 could have influenced cell migration of NPC cells." (PMID 26949513, 2016). "Also, the IHC positive rate of AKR1B10 is 83.0% in PHC tissues and 25.5% in peri-tumor tissues." (PMID 26948042, 2016). "Hence, in addition to ascorbic acid, quercetin might potentiate the anti-tumor properties of BLE by down-regulating the expression of ADH4, AKR1B10 and AKR1C2, thus preventing the degradation of methylglyoxal." (PMID 27635343, 2016). "Given the negative correlation of AKR1B10 expression levels with tumor size, we hypothesized that AKR1B10 could influence cell proliferation of NPC cells." (PMID 26949513, 2016). "However, the negative correlation with CD8+ T cells may indicate that in some cases, the increased expression or activity of AKR1B10 may inhibit the function or number of CD8+ T cells, and thus lead to the weakened immune response of the immune system to infection and tumor." (PMID 38802416, 2024). "Therefore, what deserves further determination is whether AKR1B10 affect EMT of tumor or not." (PMID 34552036, 2021).
tumor (continued). "Furthermore, slides 13 and 14 show negative staining of the tumor cells for AKR1B1, which competitively inhibits AKR1B10, which explains why the patient remained refractory to treatment." (PMID 40142797, 2025). "In addition, when we evaluated liver tissues of five patients with HCC, the protein expression of AKR1B10, ZNF468, annexin A2 (ANXA2), and CD24 was increased in tumor tissue compared with surrounding nontumor tissues." (PMID 35563425, 2022). "Depletion of AKR1B10 had no obvious effect on the body weight of the mice, but significantly enhanced the proliferative capacity of the CRC cells, which was manifested as increased tumor size and weight compared to control group." (PMID 32615540, 2020).
infection (4 papers, 2017 to 2024). The state of being infected such as from the introduction of a foreign agent such as serum, vaccine, antigenic substance or organism. "In addition, genes related to glycerolipid metabolism (Plpp2), glycolysis metabolism (Pfkp), adipocyte differentiation (Rapgef4), nucleotide metabolism (Entpd3), serine catabolism (Shmt1), retinol metabolism (Akr1b10), and lipid-grading metabolism (Pla2g4f) were upregulated after EgPSC infection." (PMID 36713407, 2022).
metabolic disorders (4 papers, 2014 to 2023). "AKR1B10 is identified as one of the top hit over-expressed genes which is associated with metabolism disorder in HCC development." (PMID 30038373, 2018). "Overall, VLPVPQK could alleviate the metabolic disorder of hepatocytes by elevating the glucose uptake and eliminating the ROS, while the HKDC1 and AKR1B10 genes might be the potential target genes and play important roles in the process." (PMID 37444365, 2023). "The correlation between AKR1B10, SPP1, B cells, DCs, and MAIT cells indicated the possible interactive network structure that may explain and control metabolic disorders and fibrotic phenotypes from NASH to HCC." (PMID 33574818, 2020).
benign neoplasm (2 papers, 2021 to 2025). A neoplasm which is characterized by the absence of morphologic features associated with malignancy (severe cytologic atypia, tumor cell necrosis, and high mitotic rate). "However, AKR1B10 expression levels in NPC tissues are lower than those in nasopharyngeal hyperplasia and benign tumors, where AKR1B10 was predominantly present in nuclei." (PMID 34063865, 2021).
digestive system tumors (2 papers, 2021 to 2024). "In the treatment of non-gastrointestinal tumors, targeted therapy of AKR1B10 has an excellent effect." (PMID 34552036, 2021). "Consequently, conducting thorough research into the connection between AKR1B10 and GI tumors holds significant promise." (PMID 39737179, 2024). "Due to differential expression of AKR1B10 in gastrointestinal tumors and other tumors, the feasibility of targeted therapy for AKR1B10 is not clear." (PMID 34552036, 2021). "However, target treatment of AKR1B10 in gastrointestinal tumors has not been thoroughly studied, and the effect of AKR1B10 in gastrointestinal tumors has not been fully elucidated." (PMID 34552036, 2021). "Despite the remarkable progress of AKR1B10 in HCC, AKR1B10 and related GWAS studies in other GI tumors are still lacking." (PMID 39737179, 2024).
digestive system diseases (1 paper, 2024). "Given that its expression is low or absent in other tissues, AKR1B10 is a potential diagnostic and therapeutic biomarker for various digestive system diseases." (PMID 39737179, 2024).
gastrointestinal disease (1 paper, 2021). A disease that occurs in the gastrointestinal system, excluding the hepatobiliary system. "However, the mechanisms underlying AKR1B10 down-regulation and its association with gastrointestinal diseases have been poorly elucidated." (PMID 34063865, 2021).
hematological malignancies (1 paper, 2020). "Among the identified seven genes (LRRC17, ZHX3, CD38, AKR1B10, LYPD6B, KIAA2022, and CMBL) in our study, CD38 was well known about its correlation with hematological malignancies." (PMID 31856408, 2020).
infectious disease (1 paper, 2018). A disorder directly resulting from the presence and activity of a microbial, viral, or parasitic agent in humans. "The function of AKR1B10 in the development of inflammatory and infectious diseases is unknown." (PMID 30320113, 2018).